LEP (leptin)
Diseases named in the same sentence as LEP in open-access papers (continued):
Sharing a sentence is not in itself a finding about the gene and the disease.
Obesity (continued). "One PTP1B inhibitor, trodusquemine, has been shown to suppress appetite, reduce body weight, and improve plasma insulin and leptin levels in a murine model of diet-induced obesity." (PMID 23092275, 2013). "Consistently, lines of epidemiologic studies have demonstrated the connection between leptin and human obesity." (PMID 23593308, 2013). "Recent evidence suggests that development of obesity involves hormones and neurotransmitters (such as leptin, cocaine- and amphetamine-regulated transcript (CART), and ghrelin) that regulate appetite and energy expenditure." (PMID 22474595, 2012). "Neonatal MSG treatment is a model of obesity in rodents which causes alterations in hypothalamic arcuate nucleus (ARC) and impairs leptin and insulin signaling in this region resulting in hyperleptinemia and hyperinsulinemia." (PMID 23216967, 2012). "Differences of leptin levels between two genders were significant at T2–5 (P < 0.001) in normal weight group, at T3–5 (P < 0.001) in overweight and obesity groups." (PMID 23316228, 2012). "We were next interested in potential effects of a sedentary lifestyle (obesity and low lean body mass) and hormones influenced by adiposity (IL-6, adiponectin, leptin) on bone density." (PMID 22455440, 2012). "At least two adipocytokines, leptin and visfatin, as well as insulin, are elevated in obesity and are known to increase eNOS." (PMID 22505944, 2012). "Global PTP1B deletion improves diet-induced obesity and glucose homeostasis via enhanced leptin signaling in the brain and increased insulin signaling in liver and muscle." (PMID 22389718, 2012). "Defects in either the ability of the BBB to transport leptin or in the response of the downstream neural circuitries to respond to leptin leads to the resistance picture of high serum leptin levels in the face of obesity." (PMID 22612379, 2012). "The effects of leptin on these obese mice sparked a leptin intense focus in obesity research over the past 15 years." (PMID 22263109, 2012). "Since they are defective in leptin signal reception, they eat more than twice as much as food compared with normal mice, resulting in obesity and diabetes." (PMID 23675258, 2012). "Most obese have increased leptin levels, indicating that in most of them obesity is a leptin-resistant state." (PMID 22284631, 2012). "Leptin expression can be increased by gastric hormones like ghrelin and as a compensatory mechanism for the leptin resistance that is frequently observed in obesity." (PMID 22682228, 2012). "For example, hepatic C-reactive protein (CRP), which is increased in obesity, binds leptin and limits leptin receptor binding and transport across the BBB." (PMID 22518191, 2012). "Leptin is a protein codified by the obesity gene (ob), secreted by the adipocytes, which acts in the Central Nervous System as a signal to regulate body weight and energy homeostasis." (PMID 22703959, 2012). "A key role for TNF-α in obesity-related insulin resistance was identified when TNF-α or TNF-α receptors were deleted in both diet-induced obese mice and leptin-deficient ob/ob mice, which resulted in significantly improved insulin sensitivity." (PMID 22110480, 2012). "The use of both DXA and leptin levels offer the opportunity for more precise characterization of adiposity and perhaps management of obesity." (PMID 22485140, 2012). "We believe that the differences observed between these two studies can be explained by at least three factors: 1) the duration of obesity; 2) the experimental diet; and 3) the proinflammatory properties of leptin." (PMID 22313574, 2012). "Fetal or neonatal abnormal nutritional environment induces leptin synthesis and secretion from adipocytes, and affects adipocyte morphology and metabolism, thus linking embryonic nutrition to adult obesity." (PMID 22958551, 2012).
Obesity (continued). "Increase of leptin level is a reliable indicator of the pubertal insulin resistance as estimated by HOMA-IR, and adiponectin can be envisioned as obesity-associated predictor of insulin resistance in puberty." (PMID 23316228, 2012). "sOb-R levels are differentially regulated in metabolic disorders like type 1 diabetes mellitus or obesity and can, therefore, enhance or reduce leptin sensitivity." (PMID 22545089, 2012). "It is therefore possible that insulin and leptin promote eNOS synthesis and NO production early in obesity, but over time, the effect of the reactive oxygen species prevails." (PMID 22505944, 2012). "The discovery and isolation of the human obese-gene and its protein product, leptin, have led to numerous subsequent studies linking leptin to obesity." (PMID 22690216, 2012). "In presence of psychological chronic stress GC lead to overeating and to obesity in spite of elevated leptin concentrations." (PMID 22701480, 2012). "A link has been described between the increased incidence of glomerulosclerosis in patients with severe obesity and serum leptin concentration." (PMID 23320148, 2012). "In summary, we observed that IUGR rats, with programmed adipocytes hypertrophy by rapid catch-up growth, were leptin resistant prior to the development of obesity." (PMID 22291999, 2012). "In fact, a condition of clear obesity can be also defined as a situation of leptin resistance with a consequent leptinemia." (PMID 23009606, 2012). "Leptin has been described as the missing link between hyperuricemia and obesity, MetS, T2DM, and related disorders." (PMID 23369448, 2012). "Leptin, the product of ob/ob gene is an important adipocyte-derived satiety factor whose plasma levels are profoundly increased in obesity in direct proportion to the degree of adiposity." (PMID 22848545, 2012). "As significant lowering of leptin impacts long term weight control, the idea of incorporating leptin adjustments into a more accurate diagnosis of obesity should be seriously considered." (PMID 22485140, 2012). "An important link has been shown between adiponectin, leptin, resistin and visfatin and obesity, insulin resistance, and related inflammatory disorders." (PMID 23320148, 2012). "The hyperleptinemia we observe in the absence of a reduction of food intake is a potential indicator of the development of leptin resistance, a common feature of obesity and an early marker of metabolic syndrome." (PMID 23285241, 2012). "Skeletal muscle resistance to the key metabolic hormones, leptin and insulin, is an early defect in obesity." (PMID 23115649, 2012). "Data also showed that mesenchymal stem cells from adipose tissue of adult ob/ob mice exhibit hyperplasia and are responsive to obesity-related endocrine factors such as leptin." (PMID 23216800, 2012). "In that model, leptin interacted with all isoforms of its receptor and we also observed improved obesity-related outcomes." (PMID 23166823, 2012). "In mice, perinatal undernutrition has been associated with an earlier occurrence of the postnatal leptin surge; while a premature leptin surge induced by exogenous leptin administration in control offspring led to accelerated high-fat-diet-induced obesity." (PMID 23189059, 2012). "As parameters of metabolic syndrome, we measured the serum levels of insulin, leptin, and adiponectin, because insulin and leptin levels are increased while adiponectin level is decreased in obesity and diabetes." (PMID 22587351, 2012). "One key feature of obesity is the development of insulin and leptin resistance, resulting in an elevation of the circulating levels of these two hormones as a consequence of compensatory physiological responses to insulin and leptin insensitivity." (PMID 21904565, 2012). "With the onset of insulin and leptin resistance, changes occur in several other obesity-related blood biomarkers, such as an increase in NEFA and triglyceride (TG) levels in the circulation, as well as in the liver and muscle tissues." (PMID 21904565, 2012).
Obesity (continued). "To further evaluate the contribution of muscle SOCS3 to leptin and insulin resistance in obesity, we generated transgenic mice with muscle-specific overexpression of SOCS3 (MCK/SOCS3 mice)." (PMID 23115649, 2012). "NONcNZO10/LtJ mice retain an intact leptin pathway but contain polygenic defects contributing to moderate and mature onset obesity and diabetes." (PMID 23056280, 2012). "The use of both DXA and leptin levels offers the opportunity for more precise characterization of adiposity and better management of obesity." (PMID 22485140, 2012). "Clinical studies have revealed hyperleptinemia in patients with heart failure, independently of obesity, and various studies have suggested leptin as a contributing factor to the development of heart failure." (PMID 22848545, 2012). "Obesity-induced leptin resistance injures numerous peripheral tissues including kidney, liver, myocardium, and vasculature." (PMID 22567283, 2012). "In our previous study, we have reported that excessive Zn in diet induces obesity, hyperinsulinemia and hypercortisolemia as a consequence of ionic imbalance of Zn, Cu and Mg resulting in oxidative stress and leptin resistance in Wistar rats." (PMID 22992416, 2012). "At a stable steady state, obesity and serum leptin levels relate to BBB transport rates and brain levels of leptin." (PMID 22612379, 2012). "Obesity increases oxidative stress, estrogen and leptin levels, inflammatory responses, energy availability, and insulin insensitivity, while decreasing adiponectin." (PMID 22257467, 2012). "Fewer studies reported an association between LEP 19 A>G, LEPR 233Q>R and risk of NHL in Chinese populations, though some previous published studies revealed that obesity was a risk factor of NHL in developed countries." (PMID 22666399, 2012). "It is very known that in obesity conditions there is an excess of leptin which is secreted by the adipocytes." (PMID 23216967, 2012). "A high leptin/adiponectin ratio has been correlated with worse metabolic and pathologic outcomes of obesity." (PMID 23056418, 2012). "Although more data are needed under each of these unique conditions to elucidate the impact sleep restriction has on leptin, it is widely considered a candidate mechanism for the development of metabolic diseases such as obesity and type 2 diabetes." (PMID 22844441, 2012). "Muscle SOCS3 is therefore positioned to play an important role in the pathogenesis of obesity-induced insulin resistance and type 2 diabetes by antagonizing both leptin and insulin signaling in skeletal muscle." (PMID 23115649, 2012). "Later in life, the leptin disruption led to a higher sensitivity to diet-induced obesity, as shown by a higher body weight gain when challenged with a high-energy diet, associated with increased adiposity and leptinemia." (PMID 22548153, 2012). "The presence of increased cytokines, in addition to the hyperleptinemia and central leptin insufficiency, seen in obesity appears to play a key role in the pathophysiology of metabolic syndrome." (PMID 22518191, 2012). "The findings of this study show a significant association between the Arg16Gly polymorphism in β2AR gene and the development of insulin resistance, overweight, and obesity in Saudi populations with an influence on the levels of lipid and leptin." (PMID 23056045, 2012). "Reduced sensitivity to leptin/insulin is widely believed to arise as a consequence of chronic positive energy balance, leading to obesity and metabolic disorders, and representing a pathological adaptation." (PMID 22833718, 2012). "Consistent with plasma leptin and adiponectin levels, leptin mRNA expression was also up-regulated, while adiponectin mRNA expression was down-regulated consistently during the development of diet-induced obesity over 24 weeks." (PMID 22947075, 2012). "In the context of obesity, the relationship between leptin/insulin, dopamine and reward behavior is paradoxical and doesn't conform to the idea just outlined." (PMID 22833718, 2012).
Obesity (continued). "Because the single congenic rat possessing only Nidd2/of locus in the genome of F344 rat showed significant yet mild hyperglycemia, this result indicates that the effect of Nidd2/of is amplified by obesity and/or the deregulation of leptin signaling." (PMID 23304119, 2012). "Leptin has been shown to negatively regulate cortisol levels in healthy mice and humans, implicating leptin as an anti-obesity factor." (PMID 22853725, 2012). "Two such factors include leptin and C-reactive protein (CRP), and both are associated with indices of obesity and cardiovascular disease." (PMID 22533665, 2012). "Moreover, if we assume obese smokers suffer from both leptin resistance, which was caused by the obesity, and insufficient leptin production, which was caused by low-grade inflammation and/or nicotine, these subjects might be more resistant to diet-therapy or to exercise-oriented weight loss." (PMID 22373492, 2012). "In fact, several previous studies revealed a strong correlation between serum leptin levels and body fat mass, suggesting that there is a leptin-resistant mechanism in obesity." (PMID 23258993, 2012). "Initially, leptin was considered an anti-obesity hormone, but experimental evidences have shown that this molecule also participates in many metabolic and endocrine processes, including the reproductive function." (PMID 22703959, 2012). "The expression of adipokines, such as leptin, is also modified in obesity and diabetes and there is a strong correlation between serum leptin and TNFα levels." (PMID 23125848, 2012). "Insulin and leptin are secreted into circulation in proportion to adipose tissue indicative of obesity in HFGP males." (PMID 22988521, 2012). "Further studies should be conducted for leptin measurements as a potentially useful tool in the management of obesity." (PMID 22485140, 2012). "Adipokines, in particular leptin and adiponectin, have attracted much attention because of their potential role in the development and progression of various obesity-related malignancies." (PMID 23173608, 2012). "Leptin and adiponectin are the most abundant cytokines produced by adipocytes and link obesity with inflammation and insulin resistance." (PMID 22984471, 2012). "Protein tyrosine phosphatase 1B (PTP1B) plays important roles in down-regulation of insulin and leptin signaling and is an established therapeutic target for diabetes and obesity." (PMID 23133528, 2012). "In support of a possible link between obesity and AD, the circulating levels of leptin are significantly lower than normal in AD patients." (PMID 22254146, 2012). "A recent study has found that changes in leptin and adiponectin levels accompanied by obesity are closely involved in immunosenescence." (PMID 22682371, 2012). "The pro-tumorigenic role of leptin on breast, colon, prostate, and ovarian cancer in patients with obesity, MetS, and T2DM was recently reviewed." (PMID 23369448, 2012). "SOCS3 is a negative regulator of leptin signaling and was recently proposed as an important therapeutic target for obesity." (PMID 22871059, 2012). "Studies show that the plasma leptin concentrations were significantly elevated in both humans and in rodent obesity models, and directly proportional to the amount of fat." (PMID 23216967, 2012). "It has recently been reported that the tissue-preserving actions of leptin are influenced by obesity." (PMID 23125848, 2012). "Recently it has been reported that extreme obesity due to the impaired leptin signalling induces alterations in subchondral bone morphology but without increasing the incidence of OA." (PMID 22910888, 2012). "In the present study we generated an animal model deficient in leptin and both B1 and B2 kinin receptors to study the influence of the KKS on the pathophisiology of obesity and T2DM." (PMID 22829877, 2012).
Obesity (continued). "However, increased obesity and leptin concentration are associated with increased sympathetic tone in some tissues, indicating that altered sympathetic innervation of the pineal gland may underlie the increased melatonin concentration in our obese non-diabetic subjects." (PMID 22623983, 2012). "Suppressor of cytokine signaling 3 (SOCS3) is a major negative regulator of both leptin and insulin signaling, thereby implicating SOCS3 in the pathogenesis of obesity and associated metabolic abnormalities." (PMID 23115649, 2012). "In opposition to most other adipocyte-derived cytokines (leptin, resistin, adipsin, etc.), adiponectin levels are decreased in obesity (probably through TNFα and IL-6 downregulation)." (PMID 22584415, 2012). "Taken together, these results suggest an additional link between SUA and cancer: with leptin regulating SUA levels in subjects with obesity, MetS, and T2DM." (PMID 23369448, 2012). "Many studies have revealed that increased inflammatory response in hypothalamus produces insulin and leptin resistance contributing to the defective food intake both in genetic or dietary fat-induced obesity." (PMID 22844271, 2012). "Inconsistencies in 24-hour plasma leptin profiles and their modulation by obesity and T2DM have been reported in the literature." (PMID 22623983, 2012). "Our results suggest that T3 modulate serum and gene expression levels of leptin, resistin, and adiponectin in experimental model of obesity, providing new insights regarding the relationship between T3 and adipokines in obesity." (PMID 22645452, 2012). "The obesity-related 16 kDa peptide leptin is synthesized primarily in white adipocytes although its production has been reported in other tissues including the heart." (PMID 22848545, 2012). "In our study, the increased levels of leptin in PsA patients were 153.7(81.3–341.1)ng/ml, which were much higher than those in Chinese obesity population (16.59±6.92)ng/ml." (PMID 23144698, 2012). "In obesity, most adipokines, including leptin, resistin and tumor necrosis factor alpha (TNFα), are overproduced and promote inflammation." (PMID 22947075, 2012). "Leptin was discovered in 1994 by Friedman and colleagues after cloning an obese (OB) gene responsible for obesity in ob/ob mice." (PMID 22518191, 2012). "To understand the influence of the KKS on the pathophysiology of obesity and type 2 diabetes (T2DM), we generated an animal model deficient for both kinin receptor genes and leptin (obB1B2KO)." (PMID 22829877, 2012). "The aim of the present study was to evaluate the antiobesity effects of the Chinese herbal formulation, LWDH, by measuring body weight, food intake, body fat mass, blood lipid profiles, and the hormones leptin and insulin using a rat model of obesity." (PMID 21904565, 2012). "Circadian patterns of leptin concentration were distinctly different between adult women with upper-body or lower-body obesity, with a delay in peak values of leptin of approximately 3 h in women with upper-body obesity." (PMID 24527263, 2012). "Leptin has been postulated to be a key mediator linking obesity and hyperuricemia as a potential regulator of SUA level." (PMID 23369448, 2012). "Since both patient groups have approximately the same BMI, this difference cannot be explained by an obesity-related leptin elevation alone." (PMID 23173608, 2012). "The positive effect of EZA on obesity and hyperlipidemia in both serum and liver was confirmed by a significant decrease of serum leptin level as compared to HFD rats." (PMID 23258993, 2012). "Increased circulating leptin, a marker of leptin resistance in obese children with Down syndrome seems to be similar to that in children with simple obesity." (PMID 23067442, 2012). "Mice with leptin deficiency (ob/ob) or deficits in its receptor (db/db) show severe obesity phenotype thus supporting a crucial role for leptin signaling to regulate feeding and energy expenditure." (PMID 23346045, 2012).